ARNT (aryl hydrocarbon receptor nuclear translocator)
Description:
Transcription factor that functions as an obligate heterodimerization partner for several basic helix-loop-helix PER-ARNT-SIM (bHLH-PAS) proteins. Forms heterodimers with the aryl hydrocarbon receptor (AHR) to mediate the transcriptional response to xenobiotics by binding xenobiotic response elements (XREs) or dioxin response elements (DREs) in target gene promoters. Also heterodimerizes with hypoxia-inducible factor alpha subunits (HIF1A, EPAS1, NPAS1 or NPAS3) to form hypoxia-inducible transcription factors that bind hypoxia response elements (HREs) and activate genes involved in cellular and systemic responses to hypoxia, including angiogenesis, erythropoiesis, and metabolic adaptation. Plays a central role in environmental sensing and developmental and physiological regulation of gene expression.
Synonyms: bHLHe2; HIF-1-beta; HIF1-beta; HIF-1beta; ARNT1; HIF1B; HIF1BETA; TANGO
Tractability: Small molecule: a structure with a bound ligand is known; a high-quality ligand is known. PROTAC: UniProt records ubiquitination sites on it; ubiquitination databases record sites on it; its protein half-life has been measured; a small molecule that binds it is known.
Target class: Transcription factor
Safety:
Unwanted effects reported when the protein is acted on. In parentheses: how it was acted on, where the effect was seen, and who reports it.
Increase, Early Life Stage Mortality (source: AOP-Wiki)
Gene: Protein-coding gene on chromosome 1 (150,808,617 to 150,876,771, reverse strand). Ensembl gene ENSG00000143437.
Subcellular location: Nucleus
Subcellular location (Human Protein Atlas): Nuclear bodies; Nucleoplasm
Pathways (Reactome):
Metabolism: Aryl hydrocarbon receptor signalling; Endogenous sterols; PPARA activates gene expression; Phase I - Functionalization of compounds; Xenobiotics
Cellular responses to stimuli: Regulation of gene expression by Hypoxia-inducible Factor
Gene expression (Transcription): NPAS4 regulates expression of target genes
Gene Ontology:
Molecular function: aryl hydrocarbon receptor binding; cis-regulatory region sequence-specific DNA binding; DNA-binding transcription factor activity; DNA-binding transcription factor activity, RNA polymerase II-specific; nuclear receptor activity; protein binding; protein heterodimerization activity; protein homodimerization activity; RNA polymerase II-specific DNA-binding transcription factor binding; sequence-specific DNA binding; sequence-specific double-stranded DNA binding; DNA-binding transcription activator activity, RNA polymerase II-specific; RNA polymerase II cis-regulatory region sequence-specific DNA binding; protein dimerization activity
Biological process: cellular response to oxidative stress; negative regulation of inflammatory response; positive regulation of glycolytic process; positive regulation of hormone biosynthetic process; positive regulation of transcription by RNA polymerase II; positive regulation of vascular endothelial growth factor production; response to hypoxia; cellular response to hypoxia; positive regulation of endothelial cell proliferation; positive regulation of erythrocyte differentiation; positive regulation of vascular endothelial growth factor receptor signaling pathway; regulation of transcription by RNA polymerase II; xenobiotic metabolic process; intracellular receptor signaling pathway; positive regulation of protein sumoylation; regulation of DNA-templated transcription
Cellular component: nuclear aryl hydrocarbon receptor complex; nuclear body; nucleoplasm; nucleus; RNA polymerase II transcription regulator complex; aryl hydrocarbon receptor complex; chromatin; cytoplasm; transcription regulator complex
Genetic constraint (gnomAD): Loss-of-function variants: 29 observed, 102.04 expected, observed/expected ratio (o/e) 0.28, 90% interval 0.21 to 0.39. The upper end of that interval is the gene's LOEUF score, 0.39, which puts it in group 1 of 6, group 1 being the genes least tolerant of losing a copy. Missense variants: 731 observed, 988.25 expected, observed/expected ratio (o/e) 0.74, 90% interval 0.69 to 0.79. Synonymous variants: 299 observed, 349.93 expected, observed/expected ratio (o/e) 0.85, 90% interval 0.78 to 0.94.
Cancer hallmarks: invasion and metastasis (suppresses); angiogenesis (promotes); change of cellular energetics (promotes)
Homologues: Orthologues: chimpanzee ARNT (99% identical), macaque ARNT (98% identical), dog ARNT (95% identical), guinea pig ARNT (94% identical), pig ARNT (92% identical), mouse Arnt (92% identical), rat Arnt (91% identical), rabbit ARNT (81% identical), tropical clawed frog arnt (74% identical), zebrafish arnt (52% identical), Drosophila melanogaster tgo (40% identical), Caenorhabditis elegans aha-1 (28% identical), and 2 more. Paralogues in human: ARNT2 (59% identical), BMAL1 (26% identical), BMAL2 (25% identical), CLOCK (21% identical), NPAS2 (20% identical), PASD1 (9% identical).
Diseases named in the same sentence as ARNT in open-access papers:
ARNT is named in the same sentence as 133 diseases in open-access papers, as found by Europe PMC text mining. Sharing a sentence is not in itself a finding about the gene and the disease. The quoted sentences say what the papers report.
breast carcinoma (26 papers, 2009 to 2024). "The AHR/ARNT heterodimer has been implicated as having importance in ER positive breast cancer and has been shown to directly associate with estrogen receptors ER-alpha and ER-beta." (PMID 22709873, 2012). "The curcumin inhibits HIF1 nuclear translocation by degrading ARNT (aryl hydrocarbon receptor nuclear translocator), which is required for the transcription of hypoxia-related genes in breast cancer stem cells." (PMID 35740529, 2022). "ARNT overexpression has been reported in breast cancer, hepatocellular carcinoma, and colon carcinoma cell lines." (PMID 23825676, 2013). "In this study, we examined the role of AHR and ARNT on ERα-dependent target gene transcription in the human MCF7 breast cancer and the human ECC-1 endometrial-cervical cancer cell lines." (PMID 22235307, 2012). "Therefore, we sought to determine the specific functions of AHR and ARNT in estrogen-dependent signaling in human MCF7 breast cancer and human ECC-1 endometrial carcinoma cells." (PMID 22235307, 2012). "The presence of AHR, ARNT and ERα at the dioxin-inducible CYP1A1 enhancer and the E2-inducible pS2 promoter has already been documented in MCF7 cells and other breast cancer cell lines." (PMID 22235307, 2012). "We used an online database (ChIPBase v2.0) to predict the transcription factors for ZNF582-AS1, chr19:56, 393, 312-56, and 414, 800 (GRCh38/hg38), and the online tool suggested five potential candidates in breast cancer cell lines, namely CTCF, KDM5B, HIF1A, ARNT, and NRF1." (PMID 35681777, 2022). "Hypoxic stress, which induces the accumulation and nuclear translocation of ARNT and HIF1A, has been shown to suppress RNAPIII recruitment and tDNA expression in cardiomyocytes and increase levels of tRNA-derived fragments in breast cancer and mammary epithelial cells." (PMID 28931413, 2017). "Consistent with other investigators' observations in breast cancer cells, we observed the recruitment of AHR and ARNT on the human CYP1A1 enhancer in a TCDD-dependent fashion and ERα was greatly enriched only after treatment with a combination of 2 nM TCDD and 10 nM E2." (PMID 22235307, 2012). "Moreover, as we previously observed that the ID4 protein controls VEGFA expression in breast cancer cells, and VEGFA in turn participates in the reprogramming of macrophages in a pro-angiogenic sense, we decided to investigate the impact of VEGFA on ID4 and ARNT expression in macrophages." (PMID 32054109, 2020). "The levels of AHR, AHR nuclear translocator (ARNT) and AHR repressor (AHRR) mRNA expression were analyzed in a cohort of 439 breast tumors, demonstrating a weak association between high AHR expression and age greater than fifty years and ERα-negative status, and HR-/ERBB2 breast cancer subtypes." (PMID 29320557, 2018).
hepatoma (15 papers, 2012 to 2026). "In a similar experiment, the ARNT-deficient mouse hepatoma cell line C4 was transiently transfected with plasmids encoding human ARNT, the lacZ gene, and the same DRE-driven luciferase gene, and control samples received empty vectors for ARNT." (PMID 22970246, 2012). "To demonstrate a requirement for ARNT in 1,2-NQ- and 1,4-NQ-dependent induction of AhR-responsive gene expression, we examined the ability of 1,2-NQ and 1,4-NQ to induce AhR-dependent reporter gene expression in wild-type (Hepa1c1c7) and ARNT-deficient (BPRc1) mouse hepatoma cells." (PMID 32526934, 2020). "TCDD has been reported to induce PAI-1 gene expression through AhR- and ARNT-dependent mechanisms in mouse hepatoma cell lines." (PMID 39596044, 2024). "A plausible model in which to address these questions is the well-established Hepa-1 c4 mouse hepatoma (Hepa-c4), which has a point mutation in the HIF-1β/ARNT gene and therefore lacks expression of HIF-1β." (PMID 36429023, 2022). "Several studies have shown that dysregulation of AHR in hepatocytes leads to steatosis and aberrant cholesterol metabolism, and increased expression of AHR and its binding partner, ARNT, has been noted in hepatocellular carcinoma (HCC)." (PMID 27283490, 2017). "In murine Hepa-1 hepatoma cells it was shown that ARNT and ARNT2 dimerize equally with the AHR in the presence of TCDD and that ARNT2 outcompetes ARNT for binding to the AHR when expressed in excess." (PMID 37696456, 2023).
melanoma (15 papers, 2009 to 2024). A malignant, usually aggressive tumor composed of atypical, neoplastic melanocytes. "In this study, the correlation between ARNT deficiency-mediated mitochondrial function and melanoma cell migration, invasion and extravasation triggered by increased ROS levels was further investigated." (PMID 33446631, 2021). "In this study, we determined that ARNT deficiency has an important impact on mitochondrial function, which in turn controls ROS levels in melanoma." (PMID 33446631, 2021). "The AhR/ARNT heterodimer upregulates cytochrome P450 expression which is associated with melanoma prognosis." (PMID 33446631, 2021). "However, we further reveal that the dysfunction of ARNT contributed to the metastasis of BRAF V600E-mutated melanoma cells." (PMID 33446631, 2021). "Nevertheless, the molecular mechanisms underlying the functional association between ARNT downregulation and tumor metastasis such as in melanoma remain unclear." (PMID 33446631, 2021). "Among the genes we identified, many are known melanoma susceptibility genes including CASP8, ARNT, and OCA2 (downregulated), PARP1, SETDB1, MTAP, SLC45A2, and MC1R (upregulated), and MX2 (both up‐ and downregulated)." (PMID 38308491, 2024). "For example, downregulation of ARNT has been demonstrated to confer melanoma metastatic potential through increasing ROS level." (PMID 38308491, 2024). "Taken together, suppression of the ARNT/PDK1 axis promotes melanoma metastasis through increased ROS production." (PMID 33446631, 2021). "It is well known that AhR dimerizes with ARNT to trigger melanoma progression, but ARNT also fulfills its multiple functions in tumorigenesis by cooperating with bHLH-PAS family members." (PMID 33446631, 2021). "The knockdown of ARNT using shRNA and siRNA approaches significantly enhanced the ROS levels in melanoma cell lines." (PMID 33446631, 2021). "Similar to our results, hypoxic responses of aryl hydrocarbon receptor nuclear translocator was shown in melanoma cell lines." (PMID 31594284, 2019). "The results also included 10 SNPs previously identified for melanoma risk reported at MC1R (2 SNPs), MX2, TERT/CLPTM1L, PLA2G6, CASP8, ACTRT3, ASIP, CDC91L1, and ARNT/SETDB1/LASS2ANXA9/MCL1/CTSK." (PMID 27993549, 2017). "Hypoxia can promote lymph node metastasis via up-regulation of PLAUR, and up-regulation of HIF1a, JUN and PLAUR in our invasive cell lines hints at possible activation of JUN/AP1 and HIF/ARNT pathways in melanoma." (PMID 20041153, 2009). "Therefore, treatment with antioxidants to prevent chemotherapy-induced melanoma metastasis should be considered in patients using anticancer drugs that target cellular metabolism mediated by the ARNT/PDK1 pathway." (PMID 33446631, 2021). "In addition, shPDK1 cells were more resistant to apoptosis than control cells upon glucose deprivation, which reveals that depletion of the ARNT/PDK1 axis reduces the dependence of melanoma cells on glucose." (PMID 33446631, 2021). "The SETDB1 gene is located on chromosome 1 at the level of the 1q21.3 region—a locus region with ten genes: this locus was identified as a melanoma susceptibility locus and contains two plausible genes for melanoma susceptibility: SETDB1 and Aryl Hydrocarbon Receptor Nuclear Translocator (ARNT)." (PMID 29156643, 2017). "Furthermore, novel germline alterations at the chromosomal region of 1q21.3 involving ARNT (aryl hydrocarbon receptor nuclear translocator) and SETDB1 (SET domain bifurcated histone lysine methyltransferase 1) were discovered lately as possible genetic risk factors for melanoma." (PMID 35628196, 2022). "In clinical tissue specimens, increased ARNT, pyruvate dehydrogenase kinase 1 (PDK1), and NAD(P)H quinine oxidoreductase-1 (NQO1) was observed in benign nevi, whereas lower expression was observed in melanoma." (PMID 33446631, 2021). "In addition, the concurrence of ARNT and PDK1 expressions was observed in melanoma tissues." (PMID 33446631, 2021).
colon carcinoma (11 papers, 2012 to 2025). "In addition, activated KRAS has been shown to induce HIF1A and ARNT target gene expression in human colon cancer cells." (PMID 34580712, 2022). "Moreover, GS suppressed viability, angiogenesis, and metastasis of colon cancer cells by inhibiting the expression of VEGF, aryl hydrocarbon receptor nuclear translocator (ARNT), STAT3 proteins, and the activity of MMP-2 and -9." (PMID 36046484, 2020).
Obesity (9 papers, 2011 to 2026). Accumulation of substantial excess body fat. "In genetically modified mice exposed to a high-fat diet, interruption of adipocyte HIF1A or ARNT, specifically, has been associated with decreased adipogenesis, prevention of obesity, and decreased instances of insulin resistance." (PMID 37899888, 2023). "In addition to ARNT, several proteins were also reported to be associated with obesity and the AhR, such as ER and NRF-2." (PMID 25942489, 2015). "Therefore, HIF1A and ARNT may be reasonable targets in terms of preventative interventions in individuals with a genetic predisposition towards obesity." (PMID 37899888, 2023). "BMI in our studied population showed a direct relationship with the transcriptional changes (downregulated) observed on selected genes (APC, ARNT, CYP2D6, LEPR, LRP12, and MYC), all of which are closely linked to the development of cancer or obesity." (PMID 35420343, 2022). "The AHR/ARNT heterodimer regulates the transcription of genes in the cytochrome P450 Cyp1 family and thousands of other genes including other nuclear receptors relevant to obesity." (PMID 32849564, 2020). "Therefore, this study was designed to investigate the role of ARNT in the skeletal muscle in the context of myofiber specification, mitochondrial biogenesis, oxidative capacity, obesity, and insulin resistance." (PMID 28005939, 2016). "ARNT could be responsible for oxidative myofiber remodeling under obesity-inducing dietary condition, which is what we tested." (PMID 28005939, 2016). "Furthermore, the human hyperphagia-associated early onset obesity mutation SIM1.R171H results in reduced reporter activation without defects in ARNT dimerization or cofactor recruitment, indicating deficits in DNA binding." (PMID 41495897, 2026). "Unlike its role in the other tissues, deletion of muscle ARNT does not affect weight gain or pathogenesis of insulin resistance and glucose intolerance in murine model of diet-induced obesity." (PMID 28005939, 2016). "Therefore, unlike ARNT in other metabolically relevant organs, skeletal muscle ARNT expression does not influence the progression of obesity and insulin resistance." (PMID 28005939, 2016).
diabetes (8 papers, 2008 to 2025). "To explore the role of ecARNT in angiogenesis during diabetes, we conducted a series of studies in mice carrying a tamoxifen-inducible, EC-specific ARNT-knockout (ArntΔEC, ERT2) mutation." (PMID 34179020, 2021). "ARNT has been implicated in the development and progression of diabetes and is severely downregulated in the liver and pancreas of patients with diabetes." (PMID 34179020, 2021). "The transcription factor aryl hydrocarbon receptor nuclear translocator (ARNT, also known as HIF1β) has been implicated in the development and progression of diabetes." (PMID 34179020, 2021). "These facts suggested that genetic variants altering ARNT function or regulation would impact glucose homeostasis and diabetes risk." (PMID 18366646, 2008). "In addition, loss of ARNT deletion in ECs exacerbated the diabetes-mediated impairment of ischemia-induced angiogenesis." (PMID 34179020, 2021). "However, the underlying mechanism in which ARNT/HIF1β is regulated in diabetes needs to be further investigated." (PMID 34290616, 2021). "We hypothesized that common polymorphisms in the ARNT gene would alter its function or expression, and in turn increase the susceptibility to diabetes by affecting glucose-stimulated insulin secretion." (PMID 18366646, 2008). "However, whether changes in ARNT activity may contribute to the vascular deficiencies observed in patients with diabetes remains unclear." (PMID 34179020, 2021). "Hence, ARNT may integrate the genetic predisposition to β-cell failure with environmental insults leading to diabetes pathogenesis." (PMID 18366646, 2008). "We began investigating the role of endothelial ARNT in diabetes by measuring ARNT expression in MVECs isolated from the hearts of diabetic mice." (PMID 34179020, 2021). "In models of type 1 [streptozotocin [STZ]-induced] and type 2 (db/db) diabetes, the abundance of ARNT protein (DB/DB) or mRNA (STZ-induced) was significantly lower in MVECs from diabetic mice than in those from non-diabetic mice." (PMID 34179020, 2021). "Although ARNT has been widely studied for its association with diabetes diseases, no literature was found to support the association between APCDD1 and diabetes diseases." (PMID 28361675, 2017). "Additionally, we focused on the role of ARNT in MVECs under hyperglycemic conditions in mice with diabetes." (PMID 34179020, 2021). "Thus, knockdown of ecARNT expression inhibits cell proliferation, which might have contributed to impaired tube formation in HG conditions, suggesting an essential role for ARNT in angiogenesis in diabetic mellitus." (PMID 34179020, 2021). "Hence, ARNT appears to play a key role in diabetes and the pathogenesis of diabetic complications." (PMID 34179020, 2021). "Thus, we conducted experiments in a line of mice carrying an inducible, EC-specific ARNT-knockout mutation (ArntΔEC, ERT2) to determine whether aberrations in ARNT expression might contribute to the vascular deficiencies associated with diabetes." (PMID 34179020, 2021). "ARNT also regulates glucose-stimulated insulin secretion in mouse β cells and is severely downregulated (by 98%) in the liver and pancreas of patients with diabetes, in addition the cardiac-specific loss of ARNT expression in mice leads to a phenotype that mimics diabetic cardiomyopathy." (PMID 34179020, 2021). "In our pilot study, the ARNT gene expression was upregulated and may have also triggered the down regulation of FOX01 and AKT with Insulin Receptor Signaling and Type 2 Diabetes Mellitus Signaling among the important canonical pathways, consistent with prior reports." (PMID 32823525, 2020).